FLNC (filamin C)
Diseases named in the same sentence as FLNC in open-access papers (continued):
Sharing a sentence is not in itself a finding about the gene and the disease.
glioma (5 papers, 2014 to 2019). A benign or malignant brain and spinal cord tumor that arises from glial cells (astrocytes, oligodendrocytes, ependymal cells). "Autoantibodies against filamin C were elevated in the patients with low-grade glioma and those against tubulin increased in the patients with nasopharyngeal carcinoma and neuroblastoma." (PMID 29360750, 2018). "FLNC expression in glioma has been reported to increase with advancing tumor grade, and serum anti-FLNC autoantibody can be a potential biomarker for early glioma diagnosis." (PMID 28031525, 2017). "Masayo Adachi-Hayama's study showed that FLNC expression was up-regulated in the glioma tissue compared with normal brain tissues and its expression level was positively correlated with the tumor histological grade." (PMID 27626164, 2016). "The present results suggest that serum anti-FLNC autoantibody can be a potential serum biomarker for early diagnosis of low-grade gliomas while it needs a large-scale clinical study." (PMID 24946857, 2014). "We found filamin C (FLNC), which is normally restricted in muscle tissues but abundantly exists in fetal central nervous system, as a candidate protein for glioma antigen." (PMID 24946857, 2014). "Serum anti-FLNC autoantibody is a useful predictor for longer survival periods in patients with both low-grade gliomas and high-grade gliomas." (PMID 24946857, 2014). "Quantitative reverse transcription–PCR (qRT-PCR) analysis of various glioma tissues and normal brain tissues confirmed that filamin C mRNA expression was significantly up-regulated in low-grade gliomas compared with normal brain tissues." (PMID 24946857, 2014). "We searched for novel glioma-associated antigens by serological identification of antigens utilizing recombinant cDNA expression cloning (SEREX), and found FLNC as a candidate protein." (PMID 24946857, 2014). "Anti-FLNC autoantibody was also detected in the serum of glioma patients, but its levels were inversely correlated with the tissue expression." (PMID 24946857, 2014). "The present study showed that FLNC protein expression increased according to tumor histological grade in glioma and the circulating anti-FLNC autoantibody was induced in low-grade gliomas or in an early stage of glioma progression." (PMID 24946857, 2014). "In this paper, we examined tissue expressions of FLNC (both in normal and tumor tissues), and investigated the serum levels of anti-FLNC autoantibody in glioma patients." (PMID 24946857, 2014). "FLNC was expressed in glioma tissues and its level got higher as tumor grade advanced." (PMID 24946857, 2014). "High-grade gliomas expressed higher level of filamin C mRNA than low-grade gliomas." (PMID 24946857, 2014). "FLNC protein expression was only observable around the nucleus of glial cells in normal brain tissue, but it spread into the whole cytoplasm and the fibrous cellular processes in the low-grade glioma cells." (PMID 24946857, 2014). "We first examined whether the expression of filamin C mRNA is elevated in the glioma tissues." (PMID 24946857, 2014).
muscular dystrophy (5 papers, 2012 to 2025). Muscular dystrophy (MD) refers to a group of more than 30 genetic diseases characterized by progressive weakness and degeneration of the skeletal muscles that control movement. "We identified causative mutations in desmin (IVS3+3A>G) and filamin C (p.W2710X), and augmented the phenotype data for individuals with muscular dystrophy due to these mutations." (PMID 23155419, 2012).
Desminopathy (4 papers, 2013 to 2020). "Out of this long list, stains for αB-crystallin, filamin-C, and myotilin are sensitive diagnostic tools to depict pathological protein aggregation in desminopathies and other forms of MFM." (PMID 23143191, 2013). "The PRM results were consistent with the relative quantification results obtained by label-free analysis, and validated the finding that desmin and FLNC are over-represented in desminopathy aggregates." (PMID 26633379, 2015). "The relative expression of desmin and filamin C (FLNC) peptides, obtained from skeletal muscle samples from desminopathy patients, was validated using PRM." (PMID 26633379, 2015). "Additional immunohistochemistry study using antibody against filamin C demonstrated filamin C aggregations in myofibers in the two patients, but not in FHLopathy or desminopathy patients (data not shown)." (PMID 33041974, 2020).
Duchenne muscular dystrophy (4 papers, 2016 to 2024). Duchenne muscular dystrophy (DMD) is a neuromuscular disease characterized by rapidly progressive muscle weakness and wasting due to degeneration of skeletal, smooth and cardiac muscle. "In limbgirdle muscular dystrophies (LGMDs) and Duchenne muscular dystrophy (DMD) patients, several Z-disc-associated proteins and sarcolemmal proteins, including FLNC and sarcoglycans, are mislocalized and form intracellular aggregates." (PMID 26929074, 2016).
Myocardial fibrosis (4 papers, 2023 to 2025). "Variants in desmoplakin (DSP) and filamin C (FLNC) have been shown to be associated with ring-like patterns of myocardial fibrosis which has been associated with worse outcomes." (PMID 38550947, 2023).
congenital myopathy (3 papers, 2017 to 2022). "We summarized the clinical information and typical features of early-onset RCM associated with congenital myopathy, arthrogryposis, camptodactyly, and torticollis due to FLNC mutations in twelve pediatric patients." (PMID 36104822, 2022).
esophageal squamous cell carcinoma (3 papers, 2017 to 2024). Esophageal squamous cell carcinoma (ESCC) is a type of esophageal carcinoma (EC) that can affect any part of the esophagus, but is usually located in the upper or middle third. "High expression of FLNC promoted lymphatic invasion and metastasis of esophageal squamous cell carcinoma by regulating Rho GTPase." (PMID 38363409, 2024). "We found that expression of FilaminC (FLNC), a member of the actin binding and cross-linking filamin protein family is correlated with lymphatic invasion and lymphatic metastasis in esophageal squamous cell carcinoma (ESCC) by increasing cell motility through activation of Rho GTPase." (PMID 28031525, 2017).
familial cardiomyopathies (3 papers, 2017 to 2025). "Previous studies have implicated FLNC in a collection of myopathies and familial cardiomyopathies." (PMID 28866788, 2017). "All candidate genes but one (SLC39A8) exhibit preferential expression in striated muscle tissues and mutations in TTN, BAG3, FLNC and FHOD3 are known to cause familial cardiomyopathy." (PMID 28296976, 2017).
familial restrictive cardiomyopathy (3 papers, 2018 to 2024). An instance of restrictive cardiomyopathy that is caused by an inherited modification of the individual's genome. "For example, mutations in filamin-C (FLNC) and αB-crystallin (CRYAB) cause familial restrictive cardiomyopathy, while novel mutations in desmin result in arrhythmogenic cardiomyopathy." (PMID 37760018, 2023).
thyroid cancer (3 papers, 2023 to 2025). "There are some molecular alterations that had never been reported in solid tumors before, including BRAF-PXK fusion, FLNC-BRAF fusion, BRAFN486_T491delinsS, PAX8C147R, PTEND252Rfs∗42, and TERTQ302R, as well as the EIF1AX c.338-2A>T splice site mutation and the KIAA1217-RET fusion in thyroid cancers." (PMID 37744220, 2023). "In this study, biological information analysis identified four genes, HSPA6, FLNC, CLDN2, and E2F1 as candidate biomarkers of thyroid cancer." (PMID 37063290, 2023).
breast carcinoma (2 papers, 2015 to 2017). "Moreover, in prostate, leukemia, and breast cancer, high expression of FLNC mRNA has been associated with better prognosis by ‘in silico’ analysis." (PMID 28031525, 2017). "We also revealed that high filamin C could predict better outcome of breast cancer (Log-rank test, p = 0.0031) and leukemia patients (Log-rank test, p = 0.044)." (PMID 25577646, 2015).
colon cancer (2 papers, 2015). "Similarly, DNA methylation of filamin C promoter in colon cancer was associated with poor survival of the patients." (PMID 25577646, 2015). "The Western blot assay indicated that FLNC, COL6A3, COL4A1 and SPON2 were abundantly expressed in the colonic fibroblasts instead of the colon cancer epithelial cells." (PMID 26338966, 2015).
Danon disease (2 papers, 2018 to 2025). A lysosomal glycogen storage disease characterized by severe cardiomyopathy and variable degrees of muscle weakness, frequently associated with intellectual deficit. "The dilated phenotype subgroup (P.1–P.10) included all patients with Danon disease, the patient with a homozygous ALPK3 variant, carriers of in-frame deletions in TTN and FLNC, a heterozygous TRIM63 missense variant, and carriers of splice-site variants in MYH7 and MYBPC3." (PMID 41440877, 2025).
esophageal cancer (2 papers, 2015 to 2017). A primary or metastatic malignant neoplasm involving the esophagus. "FLNC knockdown in esophageal cancer cell lines decreased cell migration in wound healing and transwell migration assays, and invasion in transwell migration assays." (PMID 28031525, 2017).
frontotemporal dementia (2 papers, 2015 to 2021). Frontotemporal dementia (FTD) comprises a group of neurodegenerative disorders, characterized by progressive changes in behavior, executive dysfunction and language impairment, as a result of degeneration of the medial prefrontal and frontoinsular cortices. "As found in the FLNC p.Ala193Thr, p.Arg159His and p.Val831Ile variants, filamin C expression is closely linked to neurodegeneration and aberrant filamin C expression is present in neuronal disease such as frontotemporal dementia." (PMID 33802723, 2021). "Here, we aimed to further assess the contribution of FLNC to frontotemporal dementia (FTD) etiology." (PMID 26555887, 2015).
ischemic cardiomyopathy (2 papers, 2013 to 2025). Ischemic cardiomyopathy is a cardiomyopathy in which a weakness in the muscle of the heart due to inadequate oxygen delivery to the myocardium with coronary artery disease being the most common cause. "Using exon array, the global mRNA splicing profile of ischemic cardiomyopathy has been investigated, and the alternative splicing of four main sarcomere genes, such as cardiac troponin T (TNNT2), cardiac troponin I (TNNI3), myosin heavy chain 7 (MYH7), and filamin C, gamma (FLNC), was dysregulated." (PMID 23766705, 2013).
Kawasaki disease (2 papers, 2013 to 2025). A rare inflammatory disease characterized by an acute febrile, systemic, self-limiting, medium-vessel vasculitis primarily affecting children. "In particular, validation of meprin A and filamin C as specific and sensitive markers of Kawasaki disease using commonly available ELISAs enables their clinical use to improve the accuracy and timeliness of diagnosis of KD." (PMID 23281308, 2013). "In addition, elevated levels of filamin C in patients with KD who did not respond to initial therapy as compared to those with complete response suggest that filamin C is a marker of Kawasaki disease activity." (PMID 23281308, 2013). "Also, elevations of urine meprin A or filamin C in patients suspected of Kawasaki disease do not appear to correlate to acute phase reactants such as ESR or CRP." (PMID 23281308, 2013).
lung carcinoma (2 papers, 2015 to 2021). "Altogether, our data show that the least expressed filamin, FLNC, has the strongest association with patient survival, is enriched in the metastatic stage IV of NSCLC, and is the only family member to significantly affect lung cancer cell migration." (PMID 33934493, 2021). "To further validate these novel players in lung cancer cell migration, we selected five candidates—DSE, CPA4, FLNC, TUBB6, and BICC1—and the positive control CDH2, which were upregulated in fast cells and also associated with poor overall survival in NSCLC patients." (PMID 33934493, 2021).
metastatic disease (2 papers, 2015 to 2021). "Significantly reduced expression of filamin C was also found in the primary squamous cell carcinomas and the metastatic tumors in the lung compared with the normal counterparts." (PMID 25577646, 2015). "Notably, FLNC was the least expressed filamin in NSCLC, but the only one controlling cell migration and correlating with patient survival and metastatic disease stage." (PMID 33934493, 2021).
myotilinopathy (2 papers, 2016 to 2017). "The identification of the ratio of myotilin to filamin C in aggregates as a highly sensitive and specific diagnostic marker for myotilinopathy underlines that proteomic analysis can be useful in differential diagnosis of myofibrillar myopathies." (PMID 26842778, 2016). "The ratio of the myotilin and filamin C proportions in aggregate samples was identified as a new diagnostic marker for myotilinopathy with a high sensitivity (100 %) and specificity (91 %) in our MFM cohort." (PMID 26842778, 2016). "Our findings in myotilinopathy presented in this work indicate that Z-disc-associated proteins, especially filamin C, desmin and their binding partners, are the most abundant components of the pathological aggregates in muscle fibers of myotilinopathy patients." (PMID 26842778, 2016). "The ratio of myotilin to filamin C in aggregate samples was identified as a highly sensitive and specific marker for myotilinopathy." (PMID 26842778, 2016).
respiratory failure (2 papers, 2017 to 2021). The significant impairment of gas exchange within the lungs resulting in hypoxia, hypercarbia, or both, to the extent that organ tissue perfusion is severely compromised. "A mouse model with genetic inactivation of Filamin C highlights the protein’s crucial role for muscle function; Filamin C deficient mice die at birth due to respiratory failure and have underdeveloped skeletal muscles." (PMID 29119312, 2017). "Whereas partial FLNC −/− mice, expressing a truncated filamin C by deletion of exons 41–48, show a severe muscular phenotype, leading to lethality due to respiratory failure, before birth, they displayed no obvious cardiac defects." (PMID 33557094, 2021).
squamous cell carcinoma (2 papers, 2015 to 2019). A carcinoma arising from squamous epithelial cells. "The lack of any change in Rho activity suggests that FLNC may activate distinct signalling pathways in GBM and squamous cell cancer cells, although additional studies are needed to evaluate this possibility." (PMID 30867563, 2019).
Alzheimer disease (1 paper, 2024). A progressive, neurodegenerative disease characterized by loss of function and death of nerve cells in several areas of the brain leading to loss of cognitive function such as memory and language. "Finally, integrin α-IIb, creatine kinase M-type, filamin C, glutamine γ-glutamyltransferase 2, and lysosomal α-mannosidase were selected as distinguishing biomarkers for healthy individuals and early-stage Alzheimer's disease patients using machine learning modeling with approximately 79% accuracy." (PMID 38436501, 2024).
atrioventricular block (1 paper, 2024). A heart block that is initiated in the atrioventricular node. "DCM patients with mutations in LMNA, PLN, RBM20, FLNC, DES, or SCN5A are associated with typical cardiac rhythm disorders ranging from atrioventricular blocks to supraventricular and malignant ventricular arrhythmias (MVA)." (PMID 39070560, 2024).
bile duct tumor (1 paper, 2025). "Single-cell RNA-seq mapping of FLNC, MAP2K1, and ABCA1 reveals highly specific, lineage-restricted transcriptional programs within the bile duct tumor microenvironment." (PMID 41373405, 2025).
breast tumors (1 paper, 2022). "Higher FLNA expression was detected in TNBC respect to luminal BC subgroup, whereas FLNB as well as FLNC expression levels were found higher in luminal breast tumors respect to TNBC." (PMID 35655319, 2022).
dementia (1 paper, 2015). Loss of intellectual abilities interfering with an individual's social and occupational functions. "Furthermore, additional proteins which were consistently altered in both the FLNC-, GRN- and VCP-unique datasets, e.g. GFAP, NPTN, DBI, PRDX6, MARCKS and BSN, are closely associated with cognitive function, dementia and pathological aging." (PMID 26555887, 2015).
embryonic cancers (1 paper, 2020). "We tested the expression of FLNA, FLNB and FLNC in different germ cell cancer tissues using an Affymetrix expression array analysis and found abundant expression of FLNA, in particular in seminonas, embryonic cancers and teratomas." (PMID 33266100, 2020).
fibrosarcoma (1 paper, 2009). A malignant mesenchymal fibroblastic neoplasm affecting the soft tissue and bone. "FLNc has been reported to be largely specific to skeletal and cardiac muscles and no data are available on FLNc expression in fibrosarcoma cells." (PMID 19915675, 2009).
Hypertension (1 paper, 2023). The presence of chronic increased pressure in the systemic arterial system. "In their study, younger age, hypertension, prior (non-)sustained VA, decreased LVEF, LV dilatation, late gadolinium enhancement (LGE) and genetic mutations (Phospholamban (PLN), Lamin A/C (LMNA), and Filamin-C (FLNC)) were significant predictors of arrhythmic events." (PMID 36131137, 2023).
limb-girdle muscular dystrophy type 1D (1 paper, 2008). "The only, remarkable exception was Filamin C (FLNC), which was found as a candidate on chromosome 7q for both the 608423 (limb-girdle muscular dystrophy type 1F) and the 603511 (limb-girdle muscular dystrophy type 1D) OMIM phenotype entries." (PMID 18369433, 2008).
liver cancer (1 paper, 2025). An epithelial or non-epithelial malignant neoplasm that arises from the liver. "To investigate the clinical relevance of CAV1, CD47 and FLNC we analysed the transcriptomic data from 67 HCC cases in the Biostorm cohort of the Storm trial, a phase 3 clinical study exploring sorafenib as an adjuvant therapy in liver cancer patients who had previously had local ablation surgery." (PMID 40715090, 2025).
lung adenocarcinoma (1 paper, 2020). A carcinoma that arises from the lung and is characterized by the presence of malignant glandular epithelial cells. "Moreover, considering the frequent alterations of THSD7B, SYNE2, GRM3, and FLNC in lung squamous cell carcinoma and lung adenocarcinoma, we investigated the applicability of ITS to NSCLC patients treated with ICIs." (PMID 32969604, 2020).
metabolic myopathies (1 paper, 2014). "VPA alters the expression of PEBP1, BHMT, MYL1, ALB and FLNC that are closely related with metabolic myopathies, myogenesis, albumin gene expression, and haemolytic anemia." (PMID 25551574, 2014).
mitral valve prolapse (1 paper, 2021). A fairly common and often benign valvular heart disorder characterized by redundancy or hooding of mitral valve leaflets so that they prolapse into the left atrium, often causing mitral regurgitation. "Very recently, a novel truncating mutation of FLNC (c201G > A; pTrp34) has also been linked to a special familiar form of arrhythmogenic bileaflet mitral valve prolapse syndrome (ABiMVPS) presenting with a combination of mitral-valve prolapse and associated electrophysiological alterations." (PMID 33557094, 2021).
myeloid leukaemia (1 paper, 2009). "Furthermore, using a label-free quantitative proteomic strategy to identify ASB2α substrates we observed that ASB2α expression also triggered degradation of the low levels of endogenous FLNc detectable in myeloid leukaemia cells." (PMID 19915675, 2009).
Noonan syndrome with multiple lentigines (1 paper, 2023). A rare multisystem genetic disorder characterized by lentigines, hypertrophic cardiomyopathy, short stature, pectus deformity, and dysmorphic facial features. "This is also the case for 8/14 syndromic HCM (CACNA1C, FLNC, PRKAG2, PTPN11 (Noonan), PTPN11 (Noonan syndrome with multiple lentigines), RAF1, RIT1, TTR), 3/12 DCM (DES, TNNC1 and TNNT2), and 2/6 ARVC (JUP, TMEM43) gene-disease pairs." (PMID 37872640, 2023).